SYTL3 (synaptotagmin like 3)
Description:
May act as Rab effector protein and play a role in vesicle trafficking. Binds phospholipids in the presence of calcium ions (By similarity).
Synonyms: SLP3; exophilin-6
Tractability: Antibody: UniProt places it where antibodies can reach, with medium confidence; its Gene Ontology location is reachable by antibodies, with medium confidence. PROTAC: ubiquitination databases record sites on it; its protein half-life has been measured.
Gene: Protein-coding gene on chromosome 6 (158,644,387 to 158,768,355, forward strand). Ensembl gene ENSG00000164674.
Subcellular location: Endomembrane system
Subcellular location (Human Protein Atlas): Nucleoli fibrillar center; Vesicles
Gene Ontology:
Molecular function: protein binding; neurexin family protein binding; calcium-dependent phospholipid binding; phospholipid binding; small GTPase binding
Biological process: exocytosis; intracellular protein transport
Cellular component: exocytic vesicle; plasma membrane; endomembrane system; membrane
Genetic constraint (gnomAD): Loss-of-function variants: 73 observed, 66.11 expected, observed/expected ratio (o/e) 1.1, 90% interval 0.91 to 1.34. The upper end of that interval is the gene's LOEUF score, 1.34, which puts it in group 5 of 6, group 1 being the genes least tolerant of losing a copy. Missense variants: 767 observed, 712.15 expected, observed/expected ratio (o/e) 1.08, 90% interval 1.01 to 1.14. Synonymous variants: 289 observed, 272.97 expected, observed/expected ratio (o/e) 1.06, 90% interval 0.96 to 1.17.
Homologues: Orthologues: chimpanzee SYTL3 (99% identical), macaque SYTL3 (94% identical), guinea pig SYTL3 (83% identical), pig SYTL3 (82% identical), dog SYTL3 (81% identical), mouse Sytl3 (80% identical), rat Sytl3 (79% identical), rabbit SYTL3 (74% identical), zebrafish sytl3 (32% identical), tropical clawed frog sytl3 (15% identical). Paralogues in human: SYTL5 (33% identical), SYTL4 (32% identical), SYTL2 (29% identical), SYTL1 (26% identical), RPH3A (18% identical), SYT6 (15% identical), SYT3 (15% identical), SYT9 (15% identical), SYT10 (14% identical), SYT15 (14% identical), SYT15B (14% identical), SYT16 (14% identical), and 19 more.
Diseases named in the same sentence as SYTL3 in open-access papers:
SYTL3 is named in the same sentence as 12 diseases in open-access papers, as found by Europe PMC text mining. Sharing a sentence is not in itself a finding about the gene and the disease. The quoted sentences say what the papers report.
hyperlipidemia (2 papers, 2021 to 2025). "In particular, we found an upregulation of SYTL3 gene recognized as increasing serum lipids and thus related to the risk of hyperlipidemia, which is one of the side effects in patients treated with guselkumab." (PMID 40963613, 2025). "Association between the haplotypes among four SNPs of the SYTL3 and two SNPs of the SLC22A3 and hyperlipidemia in the Han and Maonan group [n (frequency)]." (PMID 34367243, 2021).
asthma (1 paper, 2020). "Among ten hub DEGs identified for the asthma-COPD, nine DEGs including SPAG6, C7orf57, SYTL3, LRRC48, TEKT3, CCDC146, CETN2, CCDC19, and C14orf45 were identified as the novel genes." (PMID 31952466, 2020).
bladder cancer (1 paper, 2020). "Six candidate variants identified, of which 2 have previously characterized tumorigenic roles: (a) Increased expression of SMOX is associated with gastric cancer, and (b) SYTL3 encodes proteins which interact with RAB27 and deregulation of this pathway is associated with bladder cancer." (PMID 32201880, 2020).
parasite infection (1 paper, 2009). "In addition to strong expression of IFNβ and CCL5 in all cell types, parasite infection induces the expression of genes involved in cell-matrix interactions (osteopontin; SPP1) carbohydrate modification (B4GT5 and B3GNT2), vesicular transport SYTL3 and T-SNARE1 and Ca2+ homeostasis STIM1 and CARKL." (PMID 19480704, 2009).
tumor (2 papers, 2021 to 2025). "For SYTL3, the only risk biomarker in our study, its knockdown enhanced the amount of bacillus Calmette-Guérin (BCG) within tumors and its suppressive effect on tumor growth." (PMID 33986754, 2021). "Regarding cytotoxicity-related genes, GZMB and SYTL3 were up-regulated in the NK1 cluster, while PFR1 (perforin) and TNFSF10 (TRAIL) were down-regulated in tumor-infiltrating iNK cells as compared to preinfusion iNK cells." (PMID 40315330, 2025).
infection (1 paper, 2012). The state of being infected such as from the introduction of a foreign agent such as serum, vaccine, antigenic substance or organism. "A separate region associated with odds of infection included SYTL3 (Synaptotagmin-Like 3) on ovine chromosome 8, and this region had the second largest odds ratio after TMEM154." (PMID 23082221, 2012). "Genes in regions associated with odds of infection included DPPA2/DPPA4 (empirical P = 0.006), and SYTL3 (P = 0.051)." (PMID 23082221, 2012).
SYTL3 also shares sentences with these, for which no sentence is quoted: coronary artery disease (1 paper); COVID-19 (1); gastric cancer (1); ischaemic stroke (1); lentivirus infection (1); type 2 diabetes mellitus (1).